ENSG00000224681 (zinc finger pseudogene)
Gene: Unprocessed pseudogene on chromosome 9 (40,332,995 to 40,333,460, reverse strand). Ensembl gene ENSG00000224681.
Diseases named in the same sentence as ENSG00000224681 in open-access papers:
ENSG00000224681 is named in the same sentence as 1 disease in open-access papers, as found by Europe PMC text mining. Sharing a sentence is not in itself a finding about the gene and the disease.
ENSG00000224681 shares sentences with these, for which no sentence is quoted: myopia (1 paper).